IL6 (interleukin 6)
Diseases named in the same sentence as IL6 in open-access papers (continued):
Sharing a sentence is not in itself a finding about the gene and the disease.
diabetes (continued). "Our study demonstrated that the administration of periodontal hydrogels containing carvacrol and magnolol in Wistar rats with periodontal disease associated with diabetes decreases the levels of IL-6 and TNF-α in gingival tissue, favoring a reduction in inflammation." (PMID 39062018, 2024). "The algorithm showed that comorbidities (diabetes, neurological diseases), invasive procedures (central venous catheter, urinary catheter), baseline inflammatory markers levels (IL-6, PCT), and creatinine were associated with an increased risk of bacterial/fungal infection." (PMID 38616284, 2024). "This role could be attributed to the pro-inflammatory effect of IL6, which acts as an induction mechanism of islet inflammation associated with diabetes." (PMID 38667300, 2024). "In multivariate linear regression analysis, TSAT was utilized as the dependent variable and associated factors (age, gender, diabetes mellitus, total cholesterol, platelet count, and IL-6) showed that platelet count, diabetes mellitus, and IL-6 were the independent factors of TSAT." (PMID 39308920, 2024). "In addition, several cross-sectional observational studies showed that patients with diastolic dysfunction and/or diabetes were associated with increased IL-6, IL-8, and CCL2." (PMID 38630423, 2024). "In the context of diabetes, a condition often accompanied by chronic inflammation, there is a legitimate concern that exogenous IL6 could exacerbate underlying inflammatory states, potentially leading to worsened diabetic complications." (PMID 38270651, 2024). "Macrophages may induce the activation of wound-healing-associated fibroblasts, while the defective macrophages in diabetes may be corrected with IL6 treatment as a promising therapy for diabetic foot disease." (PMID 38270651, 2024). "TSAT was associated with age, sex, diabetes mellitus, total cholesterol, platelet count, and IL-6." (PMID 39308920, 2024). "Cross-sectional multivariable regression model between sRAGE levels and clinical traits (history of diabetes and cardiovascular diseases) and inflammatory biomarker levels (Il-6 and CRP) revealed a significant inverse association between circulating sRAGE levels and CRP levels." (PMID 37198231, 2023). "It is already described that patients can establish a chronic inflammation state under diabetic conditions, characterized by a decompensated secretion of pro-inflammatory cytokines, such as TNF-α, IL-1β and IL-6, and it is suggested as the major cause of comorbidities related to diabetes." (PMID 37122742, 2023). "In addition, diabetes causes a hyperglycemia-induced upregulation of proinflammatory cytokines including IL-6." (PMID 36675812, 2023). "In the present study, the impact of elevated IL-6 level on CV outcome was also significant even when classical CV risk factors (age, male gender, body mass index, smoking, history of diabetes mellitus, hypertension, hyperlipoproteineamia) were taken into account (hazard ratio: 1.29, p = 0.032)." (PMID 38067150, 2023). "The risk of all-cause death was significantly associated with older age, low BMI, diabetes mellitus, low levels of hemoglobin, albumin, and creatinine, the higher half of IL-6, past history of CVD, and malignancy in the unadjusted Cox proportional hazards model." (PMID 35155493, 2022). "Diabetes during pregnancy is associated with elevated maternal insulin, leptin and IL-6." (PMID 35197933, 2022). "Moreover, they are also recognized as adipocytokines with fairly negative impacts on insulin signaling; the combination of TNF-α and IL-6 had an impact on progressive pancreatic β-cell loss during the progression of diabetes." (PMID 36299624, 2022). "Twelve univariate variables, including age, sex, underlying pulmonary diseases, diabetes mellitus, the counts of all tested lymphocyte subsets, and IL-6, were selected to perform multivariate logistic regression analysis to identify independent predictors of ICU admission." (PMID 35346253, 2022).
diabetes (continued). "C-reactive protein (CRP) is independently associated with the occurrence of atrial fibrillation, and elevated tumor necrosis factor-α (TNF-α) and interleukin-6 (IL-6) also increase the risk of type 2 diabetes mellitus, coronary heart disease and atherosclerosis." (PMID 36361072, 2022). "Large population studies have reported elevated IL-6 levels as a predictor of diabetes risk." (PMID 36290594, 2022). "For example, if hypertension or diabetes is poorly controlled, fluctuations of sugar or blood pressure may contribute to overexpression of interleukin-6 (IL-6)which were associated with oxidative stress-lung injury and PAH." (PMID 35740313, 2022). "However, linear regression analyses demonstrated that older age was independently associated with IL-6 levels; also, older age and diabetes were independently associated with TNF-a levels in serum." (PMID 36419783, 2022). "Microbial-dysbiosis in the gut of patients with diabetes and the role of the gut microbiota in regulating various diabetes-associated metabolisms, such as glucose homeostasis, oxidative stress, and T2D-associated pro-inflammatory cytokines (IL-1 and IL-6), is well documented." (PMID 36618686, 2022). "Diabetes can be chronically associated with mild-to-moderate anemia through different ways, such as elevating the level of proinflammatory cytokines like interleukin-6 that has antierythropoietic actions, and reduction of the erythropoietic hormone as a result of nephropathy." (PMID 35139138, 2022). "In a review article on 5601 people with type 2 DM and 17,019 healthy subjects, there was evidence that the G174C polymorphism of the IL-6 gene was associated with type 2 DM, and those with the C allele were 9% more likely to develop diabetes than those with the GG genotype." (PMID 33767783, 2021). "Subsequently, these variables were included in the multivariable logistic regression model, which indicated that older age, hypertension, diabetes, dyspnoea, lymphocytes, Fbg, CTnI, IL-6, and serum ferritin were all independently associated with disease aggravation." (PMID 33850192, 2021). "Moreover, it has been reported that C-reactive protein and IL-6 are associated with hyperglycemia and the development of diabetes and that the presence of a high level of Fe favors inflammatory responses." (PMID 33920401, 2021). "Proinflammatory cytokines including TNF-α, IL-6 and IL-1β are notable cytokines that rapidly responds to oxidative damages and they have been extensively implicated in central and peripheral inflammatory reactions in diabetes." (PMID 34733158, 2021). "Interestingly, single-nucleotide polymorphisms (SNPs) in the promoter region of IL-6 (rs1800797) have been linked to increased risk of diabetes and several metabolic syndrome phenotypes, further supporting a role for IL-6 in skin metabolic processes." (PMID 34295313, 2021). "Upon exposure to diabetic stress consisting of hyperglycemia, tumor necrosis factor (TNF), and interleukin-6 (IL-6), these capillaries underwent massive thickening in the basement membrane as evidenced by collagen IV staining, a hallmark of diabetes-induced vasculopathy." (PMID 33790786, 2021). "IL-6 and its receptor trans-signaling represent an important cytokine axis in the pathogenesis of inflammation-associated disorders, including cardiovascular diseases and diabetes." (PMID 35366257, 2021). "Similarly, the presence of diabetes and elevated IL-6 levels, and exposure to interval dialysis were associated with an increased risk of severe COVID-19 infection among inpatients by univariable and multivariable analyses." (PMID 34506533, 2021). "On the basis of above evidence, it is reasonable to speculate that IL‐6 gene is a possible candidate in susceptibility to the development of diabetes." (PMID 33960655, 2021). "Finally, the proportion of BMI-associated risk of diabetes mediated by IL-6 levels was below 5%, ~3–4 times smaller than for coronary disease." (PMID 33096487, 2020).
diabetes (continued). "In addition, pro-inflammatory cytokines IL-6 and IL-8 are associated with various diseases including ARDs, such as cancer, diabetes, cardiovascular diseases, multiple sclerosis, asthma, rheumatoid arthritis, and so on." (PMID 32751398, 2020). "G/C polymorphism at the position-174 in IL-6 promotor region (rs1800795) has been found to correlate with retinopathy, nephropathy, increased albumin-to-creatinine ratio as well as poor glycemic control and hyperlipidemia in Type 1 diabetes mellitus (T1DM)." (PMID 33016995, 2020). "Additionally, inflammatory markers, such as IL-6 are related to diabetes risk, metabolic syndrome, and an increased loss of muscle mass and muscle strength." (PMID 33364510, 2020). "It is possible that enhanced glycaemic response to inflammatory stimuli may explain part of the associations between higher IL-6 mediated inflammation and higher diabetes risk observed in this study." (PMID 33096487, 2020). "Intermittent fasting is linked to improvement in the levels of biomarkers associated with cardiovascular health (blood pressure), diabetes (insulin and glucose levels), oxidative stress (8-isoprostane) and inflammation (IL-6, CRP)—suggestive of a systemic impact." (PMID 31426866, 2019). "Given the crucial role of IL-6 in wound healing and its altered expression during diabetes, it was hypothesized that changes in IL-6 expression or signaling may be associated with delays in diabetic wound healing." (PMID 31073533, 2019). "Our findings were similar to a cross-sectional study from Scotland, which has shown that IL-6 was associated with estimated lifetime cognitive status after adjusting for vocabulary, education level, cardiovascular dysfunction, duration of diabetes, and glycemic control in older patients with T2D." (PMID 31296192, 2019). "Importantly, IL-6 signalling is implicated in mediating the vascular complications of diabetes and the development of NIH and accelerated atherosclerosis responsible for SVGF." (PMID 30719343, 2019). "While both diabetes and hyperglycemia increase circulating IL-6 levels, it is unclear whether altered IL-6 is a cause or an effect of diabetes." (PMID 31073533, 2019). "Pro-inflammatory molecules such as C-reactive protein (CRP), interleukin-6 (IL-6) and tumor-necrosis factor alpha (TNFα) are associated with major chronic conditions, including diabetes, cardiovascular diseases, and age-associated conditions such as frailty and dementia." (PMID 31426866, 2019). "Secondly, higher MPV might partly be due to the regulation of some cytokines, such as IL-6,which could increase the incident diabetes risk by damaging the body’s glucose stability and β-cell function." (PMID 29651306, 2018). "In fact, several studies have also reported the regulatory roles of T-helper cell cytokines in multiple low doses of streptozotocin (MLD-STZ) diabetes model, suggesting the pathogenic role of IL-17 and IL-1β and protective role of IL-6, IL-10, and IL-4 in MLD-STZ mice." (PMID 29317893, 2017). "Our results suggest that the contribution of diabetes to breast cancer risk might be modified by IL-6 rs1800796 and HSPD1 rs2605039." (PMID 28591216, 2017). "Future studies should explore the association of inflammation with pre-diabetes and diabetes using more specific inflammatory markers like Interleukin 6 (IL-6) and use viral load as marker of severity of HIV infection in assessing predictors of dysglycemia among HIV patients." (PMID 28137307, 2017). "In the retina and kidneys of WT mice with diabetes, increased expression of inflammatory markers (IL-6, TNFα, IL1β) in association augmented expression of ECM proteins (collagen 1αIV, fibronectin) and NF κB-P65 were observed, compared to WT non-diabetic controls." (PMID 28301595, 2017). "In summary, our results suggested that diabetes was associated with breast cancer risk in the Chinese population, which may be modified by genetic variations of IL-6 rs1800796 and HSPD1 rs2605039." (PMID 28591216, 2017).
diabetes (continued). "Wogonin has been proved to mitigate inflammation, hyperglycemia, and dyslipidemia, exerting beneficial effects on diabetes and diabetes-associated diseases with elevated adiponectin expression, decreased IL-1β, IL-6, and TNF-α production, and inhibited Th17 differentiation and NF-κB signaling." (PMID 28736524, 2017). "IL-6 is a human cytokine involved in a broad range of biological functions, e.g. acts as pro-inflammatory cytokine and anti-inflammatory myokine; it is associated with a number of inflammatory diseases, e.g. rheumatoid arthritis, atherosclerosis, diabetes." (PMID 28619018, 2017). "IL-6 is a classical inflammatory cytokine considered to be a risk factor for the onset of diabetes." (PMID 29085434, 2017). "Interestingly, increased expression of Igfbp5 and other Igfbps in the muscle has been demonstrated in other than aging scenarios, for example in diabetes also associated with changes in IL‐6 levels." (PMID 26762731, 2016). "Moreover, we found that MTF treatment also significantly reduced IL6 levels in GK rats, suggesting anti-inflammation effects, since IL6 is associated with vascular smooth muscle contraction in rat models of diabetes." (PMID 27995148, 2016). "IL-6 is a pleiotropic cytokine that has both protective and pathogenic roles in diabetes." (PMID 27783671, 2016). "We observed a significant positive association between PM10 and diabetes among homozygous carriers of the pro-inflammatory major G-allele of IL6 -572G > C [Odds ratio: 1.53; 95 % confidence interval (1.22, 1.92); Pinteraction (additive) = 0.003 and Pinteraction (recessive) = 0.006]." (PMID 26911440, 2016). "Inability to fight infection especially in such cases as diabetes associated foot ulcers may also be due to dysfunctional neutrophils as a result of elevated homocysteine and IL-6 levels, and persistent hyperglycemic conditions." (PMID 27811985, 2016). "IL-6 is linked to substantial morbidity risks through arterial plaque formation, which can lead to cardiovascular disease and risks, high BMI, chronic pain, and an elevated risk for diabetes." (PMID 25983695, 2015). "Circulating levels of IL-6 have been reported to be positively associated with MS, IR and diabetes." (PMID 26578976, 2015). "Elevated hepatic IL-6 levelscan induce chronic inflammation to cause IR and promote diabetes." (PMID 26317615, 2015). "The observation that HUVECs, exposed to high glucose and palmitate, display an increased release of IL-6 is well in line with previous studies that have associated elevated IL-6 in response to palmitate in HCAECs as well as high circulating levels in patients with diabetes and CVD." (PMID 25938443, 2015). "In addition, the IL6 rs2069869 GG is associated with mortality from influenza A (H1N1) infection in the presence of diabetes." (PMID 26657940, 2015). "PCA component 2 (in which IL-6, IL-1β, and IL-8 loaded highly) was significantly associated with poorer gingival condition (OR 1.60, 95% CI 1.09–2.34; p-value 0.016) after adjustment for age, duration of diabetes, HbA1c, BMI, and sex." (PMID 25915398, 2015). "The stepwise Cox regression model construction identified the same significant predictors of survival consistently in all three models: age at admission, ejection fraction, left main stenosis, BMI, diabetes, and polymorphism rs1800795 (−174 G/C) in the IL-6 gene." (PMID 25526459, 2014). "Previous studies have demonstrated the influence of a variety of pro-inflammatory cytokine polymorphisms, including tumor necrosis factor alpha (TNFα) (rs1800629) and interleukin 6 (IL-6) (rs1800795 and rs1800797) in the risk of central obesity, diabetes and MetS phenotypes." (PMID 23306188, 2013). "Inflammation, which is the body's normal response to injury and disease, affects insulin signaling and increases beta-cell death, and markers of inflammation such as raised blood levels of C-reactive protein and interleukin 6 are associated with future diabetes risk." (PMID 23843750, 2013).
diabetes (continued). "Moreover, we recently showed that the IL-6 gene promoter polymorphism -174 was associated with new-onset diabetes after transplantation." (PMID 21766010, 2011). "In patients with type 2 diabetes mellitus, aerobic exercise during 16 weeks was associated with a decrease in bodyweight by only 1.3 kilograms and by lower plasma concentrations of IL-6, IL-18, CRP and resistin showing an anti-inflammatory effect of exercise with only marginal weight reduction." (PMID 21276223, 2011). "IL6 encodes a cytokine which is secreted to serum and induces a transcriptional response involved in a wide variety of inflammation-associated conditions, including MetS and type 2 diabetes mellitus (T2DM)." (PMID 20406432, 2010). "A number of recent studies investigated the clinical impact of the IL-6 promoter polymorphisms on different major diseases such as chronic obstructive pulmonary disease, viral infections, gout, osteoporosis, diabetes or allograft survival." (PMID 20003261, 2009). "Elevated serum IL-6 levels have been implicated in many different conditions characterized by chronic inflammation, including viral and bacterial infections, autoimmune disease, ischemia, diabetes mellitus, severe exercise, and malignancy." (PMID 19457231, 2009). "Mice with diabetes mellitus (DM) exhibit greater susceptibility to encephalitozoonosis, which manifests as higher levels of IL-6." (PMID 40920877, 2025). "Nevertheless, while the precise mechanisms remain unclear, our findings suggest that increased levels of IL-1RA may mediate the association between BMI and IL-6, potentially moderating the metabolic effects of IL-6 by reducing susceptibility to diabetes mellitus." (PMID 39201638, 2024). "The significant differences in IL-6 levels between groups underscore its role in the inflammatory processes associated with diabetes complications, suggesting that monitoring IL-6 levels could provide valuable insights into disease progression and guide therapeutic interventions." (PMID 39280507, 2024). "IL‐6 mediates pathological pain related to peripheral nerve injury, and IL‐6 treatment caused marked improvements in several measures of somatic sensory and motor nerve function of conduction velocities, tactile allodynia, and thermal hyperalgesia in experimental diabetes." (PMID 37795833, 2024). "Additionally, participants with severe periodontitis presented more cardiovascular risk factors (BMI, smoking, diabetes, and hypertension), higher overall medication intake, as well as higher inflammatory biomarker levels (IL6 and hsCRP) (1.77 vs. 1.45 and 0.13 vs. 0.10)." (PMID 37513653, 2023). "Since its identification in 1986 by molecular cloning of B-cell stimulatory factor-2, IL-6 has been recognized as a cytokine with various biological activities implicated with a detrimental role in a wide range of inflammation-associated disease states, including susceptibility to diabetes mellitus." (PMID 36200436, 2023). "We measured traditional CVD risk factors [blood pressure, Body Mass Index (BMI), diabetes, age, sex, smoking], serum markers of systemic inflammation (hsCRP, GlycA) and metabolic dysfunction (cholesterol efflux capacity), and inflammatory cytokines (IL-1β, IL-6, IL-12/IL-23, IL-17A, TNF-α, IFN-γ)." (PMID 35720288, 2022). "Over the past two decades, several studies have focused on the association between a common polymorphism (rs1800795) from interleukin-6 (IL-6) gene and Diabetes Mellitus (DM) risk." (PMID 35840989, 2022). "Many chronic illnesses including endothelial dysfunction, diabetes mellitus, cardiovascular diseases, malignancy, autoimmune disorders which, as shown in the studies, were associated with vitamin D were also similarly associated with adropin, IL-1β, IL-6 and oxidative stress." (PMID 36326375, 2022).